Y_RNA (Y RNA )
Gene: Miscellaneous RNA gene on chromosome 7 (102,336,869 to 102,336,970, forward strand). Ensembl gene ENSG00000200552.
Homologues: Orthologues: chimpanzee Y_RNA (100% identical), pig Y_RNA (73% identical). Paralogues in human: Y_RNA (100% identical), Y_RNA (99% identical), Y_RNA (93% identical), Y_RNA (90% identical), RNY3 (89% identical), RNY3P1 (88% identical), Y_RNA (87% identical), Y_RNA (86% identical), Y_RNA (85% identical), Y_RNA (84% identical), RNY3P13 (83% identical), RNY3P14 (83% identical), and 98 more.